IL10 (interleukin 10)
Diseases named in the same sentence as IL10 in open-access papers (continued):
Sharing a sentence is not in itself a finding about the gene and the disease.
Sepsis (continued). "Moreover, cytokine IL-10 inhibits the expression of Class II major histocompatibility complex (MHC) proteins (HLA-DR, HLA-DMA, and HLA-DMB) on the surface of macrophages and monocytes, which in addition to TGF-β, suppresses T-cell proliferation, contributing to immunosuppression in sepsis." (PMID 38235139, 2023). "Considering the dual role that IL-10 may play in MDSC development and function, an antibody depletion approach was used to abrogate this cytokine strictly during the sepsis challenge, thereby removing any effect that lack of IL-10 might have on MDSC development." (PMID 37681975, 2023). "IL-10 is a potent anti-inflammatory mediator that reduces neutrophil infiltration, cytotoxicity, and inflammatory responses induced by intraoperative hemorrhage, regardless of sepsis-induced gastrointestinal function or postoperative gastrointestinal dysfunction." (PMID 35388311, 2022). "Thus, IL-10 may counteract the negative effects of excessive cytokine production in sepsis patients and play an important role in the pathogenesis of sepsis." (PMID 35937269, 2022). "Studies have reported that cytokines (TNF-α, IL-10, and TGF-β) could regulate apoptosis by regulating the activity of caspase-8 in the death-induced signaling complex or changing death or survival factor levels, which control the Fas apoptotic pathway in sepsis." (PMID 33954185, 2021). "At inclusion, cases complicated with severe sepsis had significantly higher plasma sCD14, IL-10, NOx levels, higher proportion of moderate/massive ascites, lower serum albumin and more episodes of overall previous infection per patients than those non-severe sepsis cases." (PMID 27861595, 2016). "However, blocking of IL-10 could not rescue the production of IL-12 of postseptic DCs, which suggests that the low production of IL-12 during sepsis is not dependent on IL-10 expression." (PMID 25821827, 2015). "Therefore, in our study groups, even though the IL-10 level was very high in some patients, IL-10 could not be used as a predictive marker related to sepsis." (PMID 22529517, 2012). "Furthermore, a recent study showed that polymicrobial sepsis greatly induced generation of inflammatory mediators in hearts, and CMs isolated from septic rodents spontaneously secreted cytokines and chemokines (IL-6, TNF-α, IL-1β, MIP-1α, MIP-2, MCP-1, KC, and IL-10) in a time-dependent manner." (PMID 23233853, 2012). "Neonates with sepsis show differential hypermethylation of the CD3G and CD3D gene promoters and hypomethylation of IL10 gene promoter compared to controls without sepsis." (PMID 40927580, 2025). "The sepsis cohort, compared to healthy, had a lower proportion of CD4+ T cells producing IL-10 without ex vivo stimulation (p=0.01)." (PMID 39935482, 2025). "Similar to previous studies, our ICU-sepsis group displayed significantly increased interleukin (IL)-18, IL-1β, IL-6, CXCL-8, IL-10 and MCP-1 compared to either or both of the ICU-non-sepsis patient and healthy cohorts." (PMID 38410714, 2024). "Neutrophils isolated from periodontitis that respond correctly to IL-10 were characterised by high CHD1 and JMJD2A expression (ICC and ChiP-Seq H3K4me3 results), opposite to sepsis-derived neutrophils, with no changes within these enzymes." (PMID 38745328, 2024). "The CD86%, neutrophil count, CRP/ALB, NLR, IL-6, IL-10, sIL-2R, CRP, and PCT levels were significantly higher, and the HLA-DR%, lymphocytes, PLT, and ALB levels were significantly lower in the sepsis group than in the non-sepsis group (all P<0.05)." (PMID 38603712, 2024). "Throughout all explored tissues, sepsis increased pro-inflammatory cytokines like TNFα, MCP-1, IL-10 and IL-6 compared to sham animals, regardless of HVEM:LIGHT blockade." (PMID 38774873, 2024). "nDNA had areas under the receiver operating characteristic (ROC) curves of 0.78 for sepsis and 0.76 for negative outcome, which were higher than those of the other DAMPs and additional biomarkers (CRP, IL-6, IL-8, and IL-10)." (PMID 39379599, 2024).
Sepsis (continued). "Of note, IL-1b, IL-6, IL-10, TNF-a, and suPAR did not significantly change during the first week of sepsis (p > 0.05)." (PMID 39272772, 2024). "Other immune markers deregulated in sepsis, such as CD16 or CD206, as well as the anti-inflammatory cytokine IL-10 and the cytokine CXCL-10, did not exhibit a clear pattern." (PMID 37047205, 2023). "The administration of BAM15 particles or BAM15 alone in LPS-induced sepsis mice attenuated inflammatory cytokines (TNF-α and IL-6 but not IL-10) in kidneys." (PMID 38140036, 2023). "In sepsis mice, the production of liver TNF-α and IL-6 was also decreased by treatment with BAM15 particles but not BAM15, while the liver IL-10 level was not affected by all treatments." (PMID 38140036, 2023). "Regardless of the pretreatment they received, sepsis equally increased the mRNA levels of TNF-α, IL-1, IL-6 (p < 0.001) and IL-10 (p < 0.01) in both groups of septic rats." (PMID 35795581, 2022). "The concentrations of IL-10 and IL-17 were significantly higher in the SAKI group than in the sepsis-without-AKI group." (PMID 35887790, 2022). "As effectors, the concentrations of IL-10 and IL-17 were significantly higher in the SAKI group than in the sepsis-without-AKI group." (PMID 35887790, 2022). "The data from clinical studies of sepsis showed that the plasma concentrations of IL-1β, IL-6, IL-8, MCP-1, IL-10, and IL-4 were significantly higher in non-survivors when compared with survivors." (PMID 32153410, 2020). "Dusp, SphK1, IL10, ATF4, VEGF, CEBP, PGC1a, and PPARg were not significantly affected by sepsis (data not shown)." (PMID 32477273, 2020). "A retrospective cohort study of the cytokine response to pneumonia found that levels of IL-6, IL-10, and TNF-α were significantly higher among those who developed severe sepsis (survivors and non-survivors) compared with those who did not." (PMID 32144519, 2020). "Male descendants of sepsis fathers, but not female descendants, exhibited lower plasma concentrations of IL-6, TNF-alpha, and IL-10 24 h after injection of LPS." (PMID 29988283, 2018). "In the present study, we found that the ratio of IL-10 to lymphocyte in non-survivors,at ICU admission was significant higher than the survivors in severe sepsis." (PMID 28628675, 2017). "The decrease of TNF production occurs without IL-10 increase, suggesting that the modulation of TNF release was not related to the overproduction of IL-10, as in sepsis-induced immunosuppression based on LPS tolerance." (PMID 27441846, 2016). "Cytokine levels TNF, IL-6 and IL-10 were highest in CAP (82%) with fatal severe sepsis and lowest in CAP with no severe sepsis." (PMID 24363503, 2013). "The protein and gene expressions of IL-10 and TGF-β1 in Tregs were significantly higher in septic patients than those without sepsis on PBD 3 to 21 (P < 0.05 or P < 0.01)." (PMID 20064232, 2010). "The observed pattern mirrors the biphasic immunopathology seen in sepsis, where MASLD patients exhibited higher baseline levels of IL17A, IL-23, IL-33, CXCL10 and TGF-β1, yet experienced steeper declines in in IL-10, IL-23, CXCL10 and TGF-β1 in comparison to non-MASLD counterparts." (PMID 40869413, 2025). "A longitudinal study of extremely low birth weight (<1,000 g) measured cytokines at days 1, 3, 14, and 21 after birth and found that IFN-γ, IL-10, IL-18, TGF-β, and TNF-α levels differed among infants who developed fungal or bacterial LOS compared with those who never developed sepsis." (PMID 38312920, 2024). "Amphiregulin was the only analyte which could distinguish Sepsis samples with low or normal CRP from No-Sepsis samples, whereas amphiregulin, IL-6 and IL-10 could all distinguish No-Sepsis samples from Sepsis samples where CRP was elevated." (PMID 38195661, 2024). "Finally, omentin-1 at sepsis onset presented a significant positive correlation only with CRP, but not with procalcitonin, IL-1β, IL-6, IL-10, or suPAR." (PMID 37241065, 2023).
Sepsis (continued). "In a randomized, double-blind, interventional clinical trial in critically ill children with sepsis or surgery, glutamine supplementation maintained HSP70 levels for longer but did not increase glutamine levels and did not influence IL-10 or IL-6 levels and outcome." (PMID 36615909, 2023). "Moreover, IL-10 levels were positively correlated with ferritin (ρ = 0.22, p = 0.047) and IL-18 (ρ = 0.33, p = 0.002) in the HBD + DIC subset but not in sepsis controls (ferritin: ρ = 0.06, p = 0.57; IL-18: ρ = 0.16, p = 0.167)." (PMID 35190900, 2022). "Future studies should therefore investigate whether other regulatory components like IL-10 or PD1/PDL1 interactions compensate for the lack of TGFβ signaling and whether TGFβ is essential during the CARS phase of sepsis." (PMID 31815088, 2019). "However, we found that non-survivors with severe sepsis compared to survivors had lower platelet count, and higher age, SOFA score, lactic acid, INR, creatinine, aPTT, APACHE-II score, serum IL-10 levels, and rate of diabetes mellitus." (PMID 28714876, 2017). "Moreover, serum levels of IL-1β, IL-2, IL-4, IL-10, IL-17, IFN-α, IFN-β and IFN-γ were not elevated in severe sepsis survivors compared with sham-operated control mice (data not shown)." (PMID 23808943, 2013). "However, IL-10 expression was not significantly altered between vehicle and DHEA treatment in the sepsis groups at any observation point (48 hours and 96 hours) in the tissue types investigated (lung and liver)." (PMID 19594900, 2009). "Nonsurviving sepsis patients had lower levels of MMP-9 (P = 0.037), higher levels of TIMP-1 (P < 0.001), lower MMP-9/TIMP-1 ratio (P = 0.003), higher levels of IL-10 (P < 0.001), and lower TNF-α/IL-10 ratio than did surviving patients." (PMID 19799791, 2009). "As such, there was an enhanced severity of sepsis in macrophage-depleted mice with CLP compared with CLP in the Lipo group, as indicated by the survival analysis, leaky gut, serum cytokines (TNF-α and IL-10, but not IL-6), serum creatinine, and alanine transaminase." (PMID 38132765, 2023). "There was no significant change in renal function after IL-10 blockade in IR mice, but in septic AKI, renal function was significantly improved after IL-10 blockade, suggesting that IL-10 reduced the proliferation of Treg cells, thereby improving the survival rate of patients with sepsis." (PMID 35251009, 2022). "The release of IL-10 by PBMCs from septic patients was rather lower than that found in controls and patients with cured Q fever, suggesting that the decreased release of TNF in severe sepsis was not related to the overproduction of an immunosuppressive cytokine such as IL-10." (PMID 27441846, 2016). "Because both IL-6 and IL-10 were found in the present study to be increased in CETPTg mice, the consequences of CETP on clinical outcome in relation with cytokine expression should be considered with caution and may not be restricted to sepsis and LPS clearance." (PMID 33500240, 2021).
autoimmune disease (532 papers, 2006 to 2026). A disorder resulting from loss of function or tissue destruction of an organ or multiple organs, arising from humoral or cellular immune responses of the individual to their own tissue constituents. "IL-10 is thought to be protective against autoimmune diseases by inhibiting pathogenic inflammation and promoting self-tolerance." (PMID 40244128, 2025). "The dysregulation of IL10 is linked to heightened immunopathology following infection and an elevated susceptibility to various autoimmune diseases." (PMID 39936078, 2025). "Considering the potential of oclacitinib to induce autoimmune diseases, we examined to identify the association of interleukin-10 (IL-10) in PAS of the dog." (PMID 40084163, 2025). "IL-10 is generally considered protective in autoimmune diseases due to its ability to suppress pathogenic inflammation and promote immune tolerance." (PMID 41009491, 2025). "As an additional diagnostic measurement, serum interleukin-10 (IL-10) levels were measured to identify its potential role in immune regulation, as decreased IL-10 has been associated with the development of autoimmune diseases." (PMID 40084163, 2025). "Several investigations have discovered that IL10 gene polymorphisms played a role in a wide range of autoimmune disorders including inflammatory bowel disease (IBD), Behcet’s disease (BD), systemic sclerosis (SS) and ankylosing Spondylitis (AS)." (PMID 38822340, 2024). "NFIL3 has been identified as an important immune regulatory factor, and its inhibition can lead to a deficiency in IL-10 expression, potentially resulting in more severe autoimmune diseases." (PMID 39555065, 2024). "The association of rs3024505(T) with several autoimmune diseases likely arises as a consequence of its contribution to STAT3-mediated IL10 downregulation." (PMID 39337678, 2024). "Dysregulation of IL-10 has been implicated in autoimmune diseases such as rheumatoid arthritis, inflammatory bowel disease, and multiple sclerosis." (PMID 38248028, 2024). "Our findings demonstrate a causative link between specific autoimmune diseases and rhinosinusitis, highlighting IL-10, CXCL10, and CD6 as potential mediators in this association." (PMID 39104791, 2024). "Interleukin-10 (IL-10) is an anti-inflammatory cytokine produced by various cells, and it has been implicated in the pathogenesis and development of autoimmune diseases and cancer." (PMID 38606172, 2024). "It was shown that an increased IL-10 level is associated with an elevated production of autoantibody in patients with autoimmune diseases via altering the regulation of B-cell bcl-2 expression." (PMID 39064007, 2024). "For instance, mesoporous silica NP- encapsulated interleukin-10 (IL-10) has been utilized to modulate the level of inflammation and associated cascades in autoimmune diseases." (PMID 38893150, 2024). "This study investigated the impact of the polymorphism rs3024505, an eQTL for the IL10 gene implicated in autoimmune disorders." (PMID 39337678, 2024). "IL-10 dysregulation is associated with an increased risk of developing many autoimmune diseases, as well as the development of immunopathology." (PMID 37763806, 2023). "STAT3 is a transcription factor activated by cytokines such as IL-6, IL-10, and growth factors, and is implicated in the activation of Th17 cell responses and autoimmune diseases as well as anti-inflammatory responses." (PMID 36882813, 2023). "The dysfunction of IL-10 secreting regulatory B cells has been linked to the pathogenesis of autoimmune disease." (PMID 37045832, 2023). "IL-10 as a common cytokine that controls the severity of inflammation is associated with several autoimmune diseases both in humans and mice and is highly important for IBD pathogenesis since both IL-10−/− and IL-10Rβ−/− mice develop spontaneous enterocolitis." (PMID 37626658, 2023). "IL-10 is a type II cytokine with anti-inflammatory activity, the loss of which is associated with autoimmune diseases." (PMID 38003291, 2023).
autoimmune disease (continued). "In contrast, deficient IL-10 levels can lead to the development of autoimmune disease and oncogenesis." (PMID 35448559, 2022). "IL-5, IL-9, IL-10, IL-23, and IL-27 are also related to the Th2 response (T-cell response associated with allergies, progressive systemic sclerosis, and autoimmune disorders)." (PMID 36439158, 2022). "Pentanoate has been linked to autoimmune disorders and inflammation as it boosts IL-10 production and suppresses Th17 cells." (PMID 36506019, 2022). "Dysregulation of IL10 is associated with an increased response to infection and also an increased risk for development of many autoimmune diseases." (PMID 35980983, 2022). "This is in line with studies in humans, showing a reduction or functional impairment of IL-10-producing Bregs in active autoimmune diseases like systemic sclerosis, ANCA-associated vasculitis, RA, or systemic lupus erythematosus." (PMID 35073310, 2022). "Dysregulation of IL10 in patients and rodent models is associated with an increased risk for development of many autoimmune diseases and infections." (PMID 35980983, 2022). "In different autoimmune disorders, IL-10 presents an altered expression due to polymorphisms in its promoter, and elevated levels of IL-10 have been detected in SLE and Sjögren’s syndrome (SS) patients." (PMID 33567734, 2021). "Dysregulation of IL-10 is linked with susceptibility to numerous infectious and autoimmune diseases in humans and mouse models." (PMID 35071278, 2021). "IL-10 helps inhibit the Th1 effector for host immune response to pathogens; thus, dysregulation of IL-10 causes immunopathology and increases autoimmune diseases." (PMID 34564576, 2021). "Fluctuations in IL-10 level led to enhanced immunopathology in response to infection as well as to increased risk of many autoimmune diseases." (PMID 34710996, 2021). "Despite all the essential roles played by IL-10, certain chronic inflammatory diseases have been linked to overproduction or inappropriate production of IL-10, such as inflammatory bowel disease and several other autoimmune diseases." (PMID 35053004, 2021). "Dysregulation of IL-10 is associated with enhanced immunopathology in response to infection as well as increased risk on the development of many autoimmune diseases." (PMID 34822503, 2021). "Pathway analysis of p38α-dependent DEGs in males revealed enrichment of DEGs within autoimmune disease-associated pathways such as rheumatoid arthritis and MS, IL-10 and death receptor signaling, and as expected, p38 MAPK-related pathways." (PMID 34707603, 2021). "In autoimmune diseases, IL-35 can induce production of IL-10 and IL-35 by Breg cells, which inhibits pathogenic Th1/Th17 cells." (PMID 32973780, 2020). "Dysregulation of IL-10 is associated with enhanced immunopathology in response to infection as well as with the increased risk for development of many autoimmune diseases." (PMID 32630798, 2020). "IL-10-producing Breg cells constitute a major population of B cells that is associated with the development of autoimmune diseases and cancers." (PMID 32764544, 2020). "The IL‐10‐secreting B cells (B10), as one of the important regulatory B (Breg) cells, are associated with autoimmune diseases, infections and tumours." (PMID 30467955, 2019). "Dysregulation of IL-10 is associated with enhanced immunopathology in response to infection as well as increased risk for development of many autoimmune diseases." (PMID 30804924, 2019). "It is well-known that CD39 Treg cells play an essential role in constraining pathogenic Th17 cells and preventing autoimmune disease, potentially involving both the IL-10 and TGF-β produced by Foxp3+CD39+ and Foxp3−CD39+ cells, respectively." (PMID 31258540, 2019). "It has been reported that the deficiency or abnormal expression of IL-10 can increase inflammatory response to microbial challenge but also lead to development of inflammatory bowel diseases (IBDs) and several autoimmune diseases." (PMID 31497013, 2019).